IRF7 (interferon regulatory factor 7)
Description:
Key transcriptional regulator of type I interferon (IFN)- dependent immune responses and plays a critical role in the innate immune response against DNA and RNA viruses. Regulates the transcription of type I IFN genes (IFN-alpha and IFN-beta) and IFN-stimulated genes (ISG) by binding to an interferon-stimulated response element (ISRE) in their promoters. Can efficiently activate both the IFN-beta (IFNB) and the IFN-alpha (IFNA) genes and mediate their induction via both the virus-activated, MyD88-independent pathway and the TLR-activated, MyD88-dependent pathway. Induces transcription of ubiquitin hydrolase USP25 mRNA in response to lipopolysaccharide (LPS) or viral infection in a type I IFN-dependent manner (By similarity). Required during both the early and late phases of the IFN gene induction but is more critical for the late than for the early phase. Exists in an inactive form in the cytoplasm of uninfected cells and following viral infection, double-stranded RNA (dsRNA), or toll-like receptor (TLR) signaling, becomes phosphorylated by IKBKE and TBK1 kinases. This induces a conformational change, leading to its dimerization and nuclear localization where along with other coactivators it can activate transcription of the type I IFN and ISG genes. Can also play a role in regulating adaptive immune responses by inducing PSMB9/LMP2 expression, either directly or through induction of IRF1. Binds to the Q promoter (Qp) of EBV nuclear antigen 1 a (EBNA1) and may play a role in the regulation of EBV latency. Can activate distinct gene expression programs in macrophages and regulate the anti-tumor properties of primary macrophages (By similarity).
Synonyms: IRF-7; IMD39; IRF-7H; IRF7A; IRF7B; IRF7C; IRF7H
Tractability: PROTAC: UniProt records ubiquitination sites on it; ubiquitination databases record sites on it.
Gene: Protein-coding gene on chromosome 11 (612,551 to 615,983, reverse strand). Ensembl gene ENSG00000185507.
Subcellular location: Nucleus; Cytoplasm
Subcellular location (Human Protein Atlas): Nucleoplasm; Cytosol
Pathways (Reactome):
Immune System: Activation of IRF3, IRF7 mediated by TBK1, IKKε (IKBKE); DEx/H-box helicases activate type I IFN and inflammatory cytokines production; Interferon alpha/beta signaling; Interferon gamma signaling; TICAM1-dependent activation of IRF3/IRF7; TRAF3-dependent IRF activation pathway; TRAF6 mediated IRF7 activation; TRAF6 mediated IRF7 activation in TLR7/8 or 9 signaling
Disease: SARS-CoV-2 activates/modulates innate and adaptive immune responses
Gene Ontology:
Molecular function: DNA binding; DNA-binding transcription factor activity, RNA polymerase II-specific; protein binding; RNA polymerase II cis-regulatory region sequence-specific DNA binding; sequence-specific double-stranded DNA binding; cis-regulatory region sequence-specific DNA binding; DNA-binding transcription factor activity; transcription cis-regulatory region binding
Biological process: cytoplasmic pattern recognition receptor signaling pathway; defense response to virus; positive regulation of DNA-templated transcription; positive regulation of interferon-alpha production; positive regulation of interferon-beta production; positive regulation of transcription by RNA polymerase II; positive regulation of type I interferon production; regulation of adaptive immune response; DNA damage response; establishment of viral latency; immune system process; innate immune response; MDA-5 signaling pathway; negative regulation of macrophage apoptotic process; negative regulation of transcription by RNA polymerase II; regulation of immune response; regulation of monocyte differentiation; regulation of MyD88-dependent toll-like receptor signaling pathway; regulation of MyD88-independent toll-like receptor signaling pathway; regulation of transcription by RNA polymerase II; regulation of type I interferon production; response to virus; positive regulation of innate immune response; regulation of DNA-templated transcription; signal transduction; and 1 more
Cellular component: chromatin; cytoplasm; cytosol; nucleoplasm; nucleus; endosome membrane
Genetic constraint (gnomAD): Loss-of-function variants: 71 observed, 48.85 expected, observed/expected ratio (o/e) 1.45, 90% interval 1.2 to 1.77. The synonymous counts are far from expectation, so gnomAD's model fits this gene poorly and the ratio says little. Missense variants: 873 observed, 627 expected, observed/expected ratio (o/e) 1.39, 90% interval 1.32 to 1.47. Synonymous variants: 427 observed, 279.91 expected, observed/expected ratio (o/e) 1.53, 90% interval 1.41 to 1.65.
Homologues: Orthologues: chimpanzee IRF7 (98% identical), macaque IRF7 (94% identical), guinea pig IRF7 (64% identical), pig IRF7 (64% identical), rabbit IRF7 (63% identical), mouse Irf7 (62% identical), rat Irf7 (62% identical), tropical clawed frog irf7 (30% identical), zebrafish irf7 (26% identical). Paralogues in human: IRF3 (23% identical), IRF6 (23% identical), IRF5 (22% identical), IRF4 (22% identical), IRF8 (18% identical), IRF9 (17% identical), IRF2 (11% identical), IRF1 (11% identical).
Diseases named in the same sentence as IRF7 in open-access papers:
IRF7 is named in the same sentence as 272 diseases in open-access papers, as found by Europe PMC text mining. Sharing a sentence is not in itself a finding about the gene and the disease. The quoted sentences say what the papers report.
viral infection (357 papers, 2005 to 2026). "In contrast, SIRT1 deficiency leads to hyperacetylation of IRF3/IRF7, suppressing innate immunity and increasing susceptibility to viral infections." (PMID 40166469, 2025). "Lesions in C57BL/6J and Irf7−/− mouse brains were associated with areas of high virus infection, most prominently in the cortex; however, lesions were also found in other areas of the brain including where there was minimal viral antigen staining." (PMID 40295675, 2024). "Briefly, after viral infection and others, IRF7 in the cytosol is activated by distinct types of innate pattern recognition receptors (PRRs), and the PRRs associated with IRF7 can be classified as cytosolic and transmembrane signaling." (PMID 37638030, 2023). "Autosomal recessive IRF7 deficiency was reported in three patients with COVID-19 pneumonia symptoms, whereby IRF7-deficient patients are generally more prone to viral infection of the respiratory tract." (PMID 37795240, 2023). "Other genes significantly up-regulated in the hsa05203 pathway were IRF3 and IRF7, which encode interferon regulatory factors that play key roles in the innate immune response to virus infection and the transcriptional activation of type-I IFN genes." (PMID 38003837, 2023). "IRF7-deficient individuals are prone to viral infections of the respiratory tract but are otherwise healthy, potentially due to residual IFN-β and compensatory adaptive immunity." (PMID 35670811, 2022). "With brief descriptions of only three patients, the range of severe viral infections and the individual penetrance of each viral infection in patients with inherited IRF7 deficiency remained unclear." (PMID 35670811, 2022). "Through nucleocytoplasmic separation and con‐focal assays, we found that this ubiquitination‐resistant mutation hardly affected the nuclear accumulation of IRF7 upon viral infection." (PMID 35792897, 2022). "By constructing a PPI network, 15 hub target genes were obtained, and the top 3 node degrees were MX2 (down-regulated in MS), DDX60 (down-regulated in MS) and IRF7 (down-regulated in MS), all of which were associated with the viral infection." (PMID 36341423, 2022). "Among these identified genes, H2-T23, H2-T24, Ifi1, Irf7, and Stat2 were involved in other virus infections, such as those caused by chikungunya virus, Duvenhage virus, and Zika virus." (PMID 34585989, 2021). "This phenotype was in agreement with the susceptible phenotype observed in Irf7-/- mice against viral infections (herpes simplex virus, encephalomyocarditis virus or influenza virus)." (PMID 32252379, 2020). "Like TRIM21, the E3 ligase RAUL adds K48-linked ubiquitin chains to both IRF3 and IRF7 and ultimately acts as a brake on the system in response to viral infection." (PMID 30984161, 2019). "The IRF3/IRF7 heterodimer is widely implicated in viral infection, inflammatory diseases and plays an important role in promoting septic shock." (PMID 31178872, 2019). "The importance of IRF7 in antiviral immunity was clearly demonstrated in IRF7 deficient mice, which are highly susceptible to viral infections." (PMID 26810609, 2016). "In the present study, we showed that TSA mediated de-repression of genes related to anti-viral response, resulting in IFN-mediated increase in expression of genes such as IRF7, and reduction in the susceptibility of LNCaP cells to viral infections." (PMID 27366948, 2016). "IRF3 and IRF7 have been implicated as positive regulators of IFN-I gene expression induced by virus infections, whereas IRF9 constitutes an IFN-stimulated gene factor 3 together with STAT1 and STAT2, and is responsible for the induction of the IRF7 gene." (PMID 24903089, 2014). "We previously reported that Oasl1 KO cells produce more IFN-I upon acute viral infection, which was caused by higher production of IRF7 proteins in KO cells." (PMID 23874199, 2013).
viral infection (continued). "Overall, the loss of IRF-5 in the setting of an IRF-3 and IRF-7 deficiency renders mice more vulnerable to viral infection and early death, approaching that seen in mice that cannot respond to type I IFN." (PMID 23300459, 2013). "IRF7 mediates the induction of IFN-III caused by viral infection." (PMID 37638030, 2023). "The importance of IRF7-dependent interferon production in anti-viral immunity has been extensively validated, and is perhaps best exemplified by human and animal studies in which genetic IRF7 deficiencies are associated with heightened susceptibility to severe (respiratory) viral infections." (PMID 34367159, 2021). "The critical importance of the IRF7-mediated forward feedback loop is supported by an in vitro study in which the percentage of IFNβ-expressing cells after viral infection was dependent on cell density, and secretion of IFNβ, and reports that IRF7 deficient patients poorly express IFNβ." (PMID 33542718, 2020). "Moreover, IRF7 deficient mice produced elevated levels of CXCL13 after virus infection and showed impaired regulation of microglia activity." (PMID 32046242, 2020). "The viral infection causes the phosphorylation and translocation of IRF7 to the nucleus and as a result the induction of expression of type-I interferons which in turn activates IRF7 transcription through STAT2." (PMID 31665046, 2019). "Human IRF7 deficiency results in lower interferon production and impaired control of influenza virus replication and IRF7-null mice are more susceptible to viral infections, with increased morbidity and mortality following infection with influenza virus." (PMID 28380049, 2017). "IRF7 was also central when the same data were analyzed for canonical pathways: overall, the genes tended to fall into pathways associated with the inflammatory response to viral infection." (PMID 27822537, 2016). "TGFB and IRF7 co-expression in the context of viral infection can drive type I interferon and ISG expression." (PMID 41272165, 2025). "Attenuation of IRF7 expression has been shown to reduce neutrophil infiltration into the BAL fluid following viral infection." (PMID 41316271, 2025). "To explore the function of bat IRF7, we detected the basal expression of batIR7 and its induced expression after virus infection." (PMID 40108733, 2025). "It was established that in chickens, IRF7 can modulate a wide range of cellular processes in the host innate immune response to viral infection." (PMID 40941368, 2025). "A transcription factor called IRF7 (Interferon Regulatory Factor 7) controls how type I interferons are expressed in response to viral infections." (PMID 41202012, 2025). "The reconstitution of IRF7 not only corrects a key limitation in the Huh7-based viral infection model by elevating IFNB responses to levels seen in PHH, but also underscores the crucial role of IRF7 in the immune response amplification phase." (PMID 40407345, 2025). "Additional expression of IRF7 will likely allow us to study the impact of the innate immune response in infected cells on viral infection more accurately." (PMID 40407345, 2025). "Mechanistically, ATG5 promotes K48-linked polyubiquitination and autophagy to degrade RIG-I and MDA5, resulting in decreased IRF7 phosphorylation and subsequent attenuation of the acute immune-inflammatory response during viral infection." (PMID 40454785, 2025). "Given the comprehensive insights from this study on innate immunity in hepatic cells upon viral infection, it becomes clear that the restoration of IRF7 expression in Huh7 and Huh7.5 cells holds significant promise for future research applications." (PMID 40407345, 2025). "Within the IRF family of transcription factors, IRF3, IRF5, and IRF7 have well-described roles in mediating antiviral and inflammatory responses downstream of diverse viral infections." (PMID 40493408, 2025).
viral infection (continued). "Irf3 is rapidly activated during the early stages of viral infection, while irf7 primarily amplifies the interferon response, sustaining the immune reaction." (PMID 40244096, 2025). "A commonly identified biomarker gene was IRF7, which is a key player in the innate immune response to viral infections by serving as a master regulator of type 1 interferon signaling once activated." (PMID 41186200, 2025). "It was found that the expression levels of EccGAS, EcSTING, IRF3/IRF7, IFNc, and ISGs were upregulated after viral infection, indicating a potential anti-RNA virus role of EccGAS-mediated IFN signaling in response to NNV infection." (PMID 38888343, 2024). "We found that DEHP significantly blunted interferon regulatory factor 7 (IRF7) in response to viral infection." (PMID 39772131, 2024). "Following viral infection, IRF7 undergoes phosphorylation, translocates to the nucleus, and binds to the Ifna gene promoter, initiating transcription." (PMID 39850902, 2024). "Interferon regulatory factor 7 (IRF7)-mediated type I interferon antiviral response is crucial for regulating the host following viral infection in chickens." (PMID 39872942, 2024). "The canonical models of type-I IFN production state that IRF3 is activated prior to IRF7 in viral infections that trigger TLRs or RIRs." (PMID 39702382, 2024). "Various irfs (e.g., irf1, irf2, irf3, irf4b, irf7, irf9, and irf10) were previously found upregulated with poly(I:C) or viral infection in teleost species." (PMID 39211041, 2024). "AIP was identified as a potential binding partner for the transcription factor interferon (IFN) regulatory factor 7 (IRF7) by a proteomics approach mapping the innate immune interactome following virus infection." (PMID 38479600, 2024). "During viral infection, IRF7 expression increases, while plasmacytoid dendritic cells (pDCs), which are characterized by high basal IRF7 expression, trigger rapid transcription of IFNA genes." (PMID 38543729, 2024). "Studies have found significant upregulation of CASP6, PTGS2, and IRF7 with the pathological process initiated by bacterial or viral infection." (PMID 38393075, 2024). "Activation of IRF7 strengthens innate immunity and facilitates the control of bacterial and viral infections, which is prevalent in inflammatory and infectious diseases." (PMID 38671352, 2024). "The expression of ISGs typically follows prominent activation of IRF3 and IRF-7 during viral infections." (PMID 39640591, 2024). "Studies have found significant upregulation of caspase (CASP6), prostaglandin-endoperoxide synthase-2 (PTGS2), and interferon regulatory factor 7 (IRF7) with the pathological process initiated by a bacterial or viral infection." (PMID 39121644, 2024). "It has been established that the antiviral activity of the host is usually associated with the elevation of IRF7 and IFN-β levels in the cells after virus infection." (PMID 39872942, 2024). "During viral infections in the respiratory tract by influenza A virus, the attenuated activity of IRF7 can ameliorate acute lung injury." (PMID 38775156, 2024). "IRF7, constitutively expressed in plasmacytoid dendritic cells and B cells and induced in many other cell types by viral infections, is the main transcription factor responsible for the activation of IFNα promoters." (PMID 36851549, 2023). "Studies have shown that IRF7 expression is responsible for the induction of interferon-I (IFN-I) secretion in the late stages of viral infection." (PMID 37446070, 2023). "The increase in sterols then participates the activation of IRF3 and IRF7 and triggers the fish’s innate immunological response to the virus infection." (PMID 36901854, 2023). "IRF7 degradation via ubiquitin‐proteasome system is additionally accelerated upon viral infection in all tested cell types, except for plasmacytoid dendritic cells (pDCs)." (PMID 37667453, 2023).